DNAAF10 (dynein axonemal assembly factor 10)
Description:
Key assembly factor specifically required for the stability of axonemal dynein heavy chains in cytoplasm.
Synonyms: WDR92; FLJ31741; Monad
Tractability: Small molecule: it has a high-quality binding pocket. PROTAC: ubiquitination databases record sites on it.
Gene: Protein-coding gene on chromosome 2 (68,122,936 to 68,157,549, reverse strand). Ensembl gene ENSG00000243667.
Subcellular location: Dynein axonemal particle
Gene Ontology:
Molecular function: protein binding; ubiquitin binding
Biological process: axonemal dynein complex assembly; protein stabilization
Cellular component: RPAP3/R2TP/prefoldin-like complex; dynein axonemal particle
Genetic constraint (gnomAD): Loss-of-function variants: 26 observed, 36.4 expected, observed/expected ratio (o/e) 0.71, 90% interval 0.52 to 0.99. The upper end of that interval is the gene's LOEUF score, 0.99, which puts it in group 4 of 6, group 1 being the genes least tolerant of losing a copy. Missense variants: 369 observed, 423.04 expected, observed/expected ratio (o/e) 0.87, 90% interval 0.8 to 0.95. Synonymous variants: 143 observed, 156.26 expected, observed/expected ratio (o/e) 0.92, 90% interval 0.8 to 1.05.
Homologues: Orthologues: chimpanzee PPP3R1 (99% identical), macaque DNAAF10 (99% identical), dog DNAAF10 (96% identical), pig DNAAF10 (96% identical), guinea pig DNAAF10 (96% identical), rabbit DNAAF10 (94% identical), mouse Dnaaf10 (94% identical), zebrafish dnaaf10 (84% identical), tropical clawed frog dnaaf10 (83% identical), rat Dnaaf10 (80% identical), Drosophila melanogaster Wdr92 (58% identical). Paralogues in human: BUB3 (21% identical), RAE1 (20% identical).
Diseases named in the same sentence as DNAAF10 in open-access papers:
DNAAF10 is named in the same sentence as 1 disease in open-access papers, as found by Europe PMC text mining. Sharing a sentence is not in itself a finding about the gene and the disease.
DNAAF10 shares sentences with these, for which no sentence is quoted: Hypertension (1 paper).